HK2 (hexokinase 2)
Diseases named in the same sentence as HK2 in open-access papers (continued):
Sharing a sentence is not in itself a finding about the gene and the disease.
cancer (continued). "HK2 is required for the development and/or growth of cancer in several cancer models, but the necessity of HK2 in T cells is not fully understood." (PMID 30140438, 2018). "Although there are four HK isoforms, the isoforms HK1 and HK2 seem to be overexpressed in cancer cells." (PMID 29629339, 2018). "Among these isozymes, both HK1 and HK2 play critical roles in promoting cell proliferation and survival in malignant cancers." (PMID 29721175, 2018). "In summary, our results demonstrated that PIM2 functions as a unique and key regulator of cancer development by virtue of its coordination of glycolysis, autophagy, and paclitaxel resistance through the phosphorylation of HK2." (PMID 29985480, 2018). "In particular, HK2 expression was suggested to be responsible for accelerated glycolysis in cancer cells." (PMID 29504907, 2018). "Hexokinase 2 (HK2) is one of the most highly upregulated metabolic enzymes in both cancer and activated T cells." (PMID 30140438, 2018). "3-bromopyruvate (3BP), another glycolysis and TCA inhibitor that targets HK2, leads to a depletion of the cellular ATP reserves, which was shown as a key determinant of chemoresistance in certain types of cancer." (PMID 29805774, 2018). "Selective inhibition of the HK1−HK2+ cancer cell-specific energy production pathways (HK2-driven glycolysis, oxidative phosphorylation and fatty acid oxidation), due to the unique presence of only the HK2 isoform, appears promising to treat HK1−HK2+ cancers." (PMID 29988332, 2018). "HK2 plays an important role both in glycolysis and apoptosis and its increased activity has been reported in several types of cancers, showing a direct relation between growth rates and HK2 activity." (PMID 29805774, 2018). "HK2, the first rate limiting enzyme for glycolysis, is highly expressed in various cancers, which enhances aerobic glycolysis." (PMID 29662084, 2018). "Taken together, our data clearly indicated that targeting the KDM1A would rewire the Warburg effect and inhibit cancer cell proliferation, by regulating the key enzyme HK2 expression." (PMID 30568590, 2018). "According to the theory proposed by Pedersen and co-workers the overexpression of the VDAC-bound HK2 is a major player in promoting the growth of aggressive cancers and this enzyme represents good target for cancer therapy." (PMID 30261663, 2018). "A doxycycline-inducible shRNA silencing system was used to examine the effect of HK2 knockdown in cultured cells and in xenograft models of HK1−HK2+ and HK1+HK2+ cancers." (PMID 29988332, 2018). "To examine the connection between HK and tumorigenesis, we analysed HK1 and HK2 expression in a number of human cancer cells using Western blotting and immunofluorescent staining." (PMID 29721175, 2018). "The dominant presence of HK2 on the mitochondria and the regulatory role of its N-domain in the inhibition of apoptosis, highlight the molecular and structural importance for the characterization of HK2 roles in the initiation and maintenance of cancer." (PMID 29298880, 2018). "Most tumors express both HK1 and HK2, and subsets of cancers from a wide variety of tissues of origin express only HK2." (PMID 29988332, 2018). "The regulatory mechanism of glycolytic flux in normal cells is subverted in cancer cells to inhibit rate-limiting steps and reengineer the glucose metabolism by inducing many glycolytic enzymes and transporters, such as HK2, GLUT1, and PDK15,19." (PMID 29662084, 2018). "We propose that our findings make HK2 an attractive target for cancer therapy, as it would be expected to have limited immunosuppressive side effects." (PMID 30140438, 2018). "While cancer cells and T cells both upregulated HK2 expression, our data indicate it is only required in the former." (PMID 30140438, 2018). "Hexokinase-2(HK-2) plays dual roles in glucose metabolism and mediation of cell apoptosis, making it an attractive target for cancer therapy." (PMID 28320429, 2017).
cancer (continued). "Recovery of glucose metabolism by overexpression of HK2 in miR-143 overexpressing cells restores the cell migration and proliferation, suggesting that the miR-143-mediated cancer suppression is through the direct inhibition of HK2." (PMID 28174335, 2017). "Results revealed that most of cancer cells elevate the expression of HK2 and LC3B in the presence of nickel." (PMID 29285270, 2017). "This evidence suggested that HK2 or the glycolysis signaling pathway remains a promising target of anti-cancer therapy." (PMID 28427230, 2017). "Based on these results, it was postulated that the E6/E7 oncogenes reprogram HPV-positive cancer cells towards glycolysis through a direct activation of HK2 expression." (PMID 29290953, 2017). "Overexpression of miR-143 inhibited cancer cells proliferation, migration, invasion, and glucose metabolism through direct targeting HK2." (PMID 28174335, 2017). "Our findings here indicated that targeting HK2 to regulate the hypoxia-regulated cancer glucose metabolism switch also contributes to the antitumor activity of miR-125a." (PMID 28596599, 2017). "The Warburg effect, which drives aerobic glycolysis in HeLa and other cancer cells, is thought to be driven by increases in HK2 and altered AKT signaling." (PMID 28962651, 2017). "In fact, HK2 has been shown to be closely related to the reprogramming of glucose metabolism in variety of cancers, allowing cancer cells to proliferate and survive though maintenance of biosynthesis and redox homeostasis." (PMID 28445985, 2017). "Among these different HKs, HK-2 is found to be expressed of high rate in malignant tumors and plays a key role in the development of Warburg phenotype." (PMID 28320429, 2017). "Integration of metabolomics and our reported transcriptomic data for this tissue unveils a link between glucose down-regulation and overexpression of HK2, an enzyme that catalyzes the first step of glycolysis and is overexpressed in cancer cells." (PMID 29137232, 2017). "A key regulatory and rate-limiting role in this process is played by the glycolytic enzyme Hexokinase 2 (HK2) which is expressed at only very low concentrations in most normal tissues but often at elevated levels in cancers." (PMID 29290953, 2017). "In cancer cells, HK2 overexpression is not only related to hyperactivated glycolysis but also associated with apoptosis resistance." (PMID 28427230, 2017). "Only HK2 is expressed at high levels in cancer cells, thus accounting for the high glycolytic rate in cancer cells." (PMID 29137232, 2017). "Aerobic glycolysis was an important cancer metabolism pathway, in which hexokinase 2 (HK2) was a crucial enzyme controlling the first step of glycolysis." (PMID 29371926, 2017). "Above all, these results suggested that Benz had glycolysis inhibitory effect on cancer cells by targeting HK2." (PMID 28427443, 2017). "And Hexokinase 2 (HK2) is most closely related to malignant tumor which expresses at higher level compared with normal cells." (PMID 28427443, 2017). "Hexokinase 2 (HK2) is highly activated in cancer cells and is located on the outer membrane of mitochondria." (PMID 27543457, 2017). "It is well known that HK2, which is found in insulin-sensitive tissues, such as skeletal muscle and adipose tissue, is the major bound HK isoform expressed in cancers." (PMID 29285270, 2017). "HK2, the first rate-limiting enzyme of glycolysis, helps cancer cell with a highly glycolytic metabolism and promotes cancer cell proliferation." (PMID 28445971, 2017). "As HK2 was a crucial enzyme involved in glycolysis, inhibiting HK2 would reduce the ATP level in cancer cells (**P < 0.01), then triggered activation of the cellular energy regulator AMP-activated protein kinase (AMPK)." (PMID 28427443, 2017). "Numerous and compelling data from laboratory and clinical investigations has revealed that HK2 was overexpressed in various types of human cancers, including NSCLC." (PMID 28427230, 2017).
cancer (continued). "It has been widely studied that HK2 regulates tumorigenesis and migration in multiple cancer types, yet the mechanisms are still poorly defined." (PMID 28174335, 2017). "Hexokinase 2 (HK2), the major isozyme contributing to aerobic glycolysis, is overexpressed in cancers and proposed as a metabolic target for cancer therapeutic development." (PMID 29043013, 2017). "Critical to cancer aerobic glycolysis is the glycolytic enzyme HK2 that catalyzes the first committed step in glycolysis." (PMID 29137232, 2017). "HK1 is highly expressed in normal tissues of the human body, and its distribution is wider than that of HK2 (only expressed in cancer cells)." (PMID 28427443, 2017). "Several previous studies have shown that inhibiting HK2 expression decreases the cancer cell survival rate as well as their metastatic potential." (PMID 27926482, 2017). "Four hexokinase isoforms (HK1-HK4) are expressed at varying levels in tissues, but HK2 is the sole isoform overexpressed in cancer." (PMID 28915575, 2017). "On the outer membrane of mitochondria, HK-2 interacts with VDAC-1 to form complex to prevent cancer cell apoptosis." (PMID 28320429, 2017). "In cancer cells, induced HK2 is mainly bound to the mitochondria and interacts with voltage-dependent anion channels (VDACs) located on the outer mitochondrial membrane." (PMID 28186160, 2017). "As a specific example, miR-143 down-regulation, found in a number of tumors, can up-regulate hexokinase 2 (HK2) expression to promote a shift towards aerobic glycolysis in cancer cells." (PMID 29257069, 2017). "MYC is involved in regulating many metabolic enzymes, such as LDHA and HK2 for glycolysis, in cancer cells." (PMID 28474697, 2017). "From the results of recent studies, HK2 is highly expressed in various cancers, and is regulated by miRNA." (PMID 29285270, 2017). "Given its selective expression in cancer, HK2 has been achieved increasing attention on its clinical implications." (PMID 28415659, 2017). "Because of the poor effect and side-effects of these compounds, developing novel potent HK2 inhibitors for treatment of CRC or other cancers is a matter of great urgency." (PMID 28427443, 2017). "The overexpression of HK-2 has been described in a wide variety of malignant tumors, indicating that HK-2 plays an important role in the development of cancer." (PMID 28445985, 2017). "This was demonstrated for cancers in which high glucose uptake was induced by over-expression of hexokinase 2 (HK2) or the MYC oncogene." (PMID 28531108, 2017). "HK2 catalyzes the first step of glycolysis and is overexpressed in many human cancers, including ESCC." (PMID 29137232, 2017). "In comparison with normal tissues, cancer cells prefer to metabolize glucose into lactic acid by glycolysis, which is known as the “Warburg effect”, and is accompanied by upregulation of HK2." (PMID 29285270, 2017). "Remarkably, only HK2 is detected to be overexpressed in cancer cells and contributed to the high glycolytic rate in tumors." (PMID 28415659, 2017). "Given its key position in glycolysis catalytic chain and selective overexpression in cancer cells, HK2 provided an attractive target for antitumor drug discovery." (PMID 28427443, 2017). "We previously reported that HG upregulates HIF-1α and induces the expression of some HIF-1 target genes, including GLUT-1 and HK2 glycolytic enzyme, that have been shown to protect from drug-induced cancer cell death." (PMID 27901482, 2017). "Compared with normal tongue tissues, the level of HK2 expression was significantly increased in primary cancer tissues." (PMID 27926482, 2017). "Overexpression of HK-2 was observed in various cancers, such as gastric, ovarian, breast cancer, cervical carcinoma, esophageal adenocarcinoma and nasopharyngeal carcinoma." (PMID 28320429, 2017). "To date, the prognostic value of HK2 in various cancers has been extensively explored in a group of original researches." (PMID 28415659, 2017).
cancer (continued). "Previous studies have confirmed that HK2 expression was significantly higher in a variety of malignant tumours." (PMID 29156804, 2017). "In particular, GLUT3, HK2, PKM2 and LDHA play critical roles in initiating and maintaining the high glycolytic rates of rapidly proliferating cancer cells, and are associated with greater dependence on glycolysis than on OXPHOS." (PMID 28467784, 2017). "A case study in a cancer patient with fibrolamellar hepatocellular carcinoma shows the clinical value of 3-bromopyruvate (3-BrP), a HK2 inhibitor targeting the glucose metabolism of cancer cells." (PMID 28009990, 2017). "Although HK2 elevation has been reported in several cancers compared to normal tissues, some normal tissues including muscle cells and normal cerebellum have HK2 protein." (PMID 27588472, 2016). "HK2 expression offers an advantage to cancer cells by increasing aerobic glycolysis, resulting in an altered metabolic state with an anti-apoptotic effect." (PMID 27260001, 2016). "Recently, numerous studies have reported that hexokinase-2 (HK2) is aberrantly expressed in cancer, indicating that HK2 plays a pivotal role in the development and progression of cancer." (PMID 27824926, 2016). "In this meta-analysis, we identified that elevated HK2 expression was significantly associated with shorter OS and PFS in patients with solid tumor, but the association varies according to cancer type." (PMID 27824926, 2016). "Various transcription factors and microRNAs are involved in the regulation of HK2 expression during cancer initiation and progression." (PMID 27260001, 2016). "Previous studies have confirmed that HK2 expression was significantly higher in a variety of malignant tumors." (PMID 27351131, 2016). "Taken together, these results are consistent and reveal the HK2 involved in multiple types of carcinoma." (PMID 26884725, 2016). "Several genes, such as CD44, KLF5, K-Ras and hexokinase 2, have been confirmed as the direct targets of miR-143 in cancer cells." (PMID 26484567, 2015). "It has been suggested that while HK1 is ubiquitously expressed in the majority of adult tissues, HK2 is expressed at high levels in many cancer cells." (PMID 25426557, 2015). "The target gene of the siRNA approach is the glycolytic enzyme hexokinase 2 (HK-2), which is predominantly overexpressed in malignant tumors and crucial for the Warburg effect." (PMID 26158266, 2015). "The first glycolytic step generating glucose-6-phosphate is catalyzed by hexokinases (HK), where in particular the HK2 isoform is strongly expressed in cancer including GBM." (PMID 25932951, 2015). "Similar to PDK1, interference with HK2 does not only affect cellular metabolism, but also induces apoptosis thereby conferring a growth advantage to cancer cells." (PMID 25932951, 2015). "The glycolytic enzyme hexokinase 2 (HK2), which is overexpressed in cancer cells, is a key regulator of the Warburg effect and binds to VDAC, forming HK–VDAC complexes." (PMID 26090338, 2015). "Although PKM2 was reduced in response to resveratrol, which was consistent with previous research, our results also suggested that HK2 is essential for resveratrol correlated metabolic changes and cancer cell growth and apoptosis." (PMID 25938543, 2015). "Despite its absence or low expression in the majority of adult normal cells, HK2 is widely over-expressed in many cancer cells." (PMID 25053988, 2014). "For example, Let-7 family regulates multiple aspects glucose metabolism in multiple organs; miR-143 regulates glucose metabolism of cancer cells by targeting hexokinase 2 isoform (HK2); miR-21 is an important target of ROS." (PMID 24895527, 2014). "In many cancer cells, hexokinase 2, an embryonic isoform with limited expression in adult tissue, is highly upregulated in cancer." (PMID 24363178, 2014). "Logistic regression analyses were conducted to determine the significance of KLK2 SNPs and hK2 levels for predicting cancer at repeat biopsy." (PMID 25279276, 2014).
cancer (continued). "RNA transcription and protein expression of HK2 and other ERVs are elevated in many cancers, some autoimmune/inflammatory diseases, and HIV infection, and there has been a long and unresolved search for a causal role in disease (5, –, 7)." (PMID 24920817, 2014). "The HK2 gene is up-regulated in cancer cells and is sometimes considered as the major gene responsible for Warburg’s glycolysis increase." (PMID 25010005, 2014). "HK2 binds to outer mitochondrial membrane and inhibits the release of cytochrome C to suppress apoptosis and promotes cell survival in cancer cells." (PMID 24911170, 2014). "A high rate of glycolysis to obtain energy is a commonly observed feature in cancers, and previous studies usually focus on miRNA roles in targeting the key enzymes of glycolysis, including hexokinase-2, and pyruvate dehydrogenase kinase." (PMID 24935220, 2014). "For example, HK2 is only expressed in limited number of adult tissues but is expressed at high levels in cancer cells." (PMID 24911170, 2014). "Collectively, for the first time we have demonstrated that everolimus inhibits glycolysis, partly by repressing mTOR signaling which then upregulates miR-143, an important cancer-related microRNA involved in the deregulation of HK2." (PMID 23251295, 2013). "HK2 also plays an important role in FDG catabolism, with its overexpression significantly associated with SUV in malignant tumors." (PMID 23718763, 2013). "In fact, HK2 was able to promote the first step of glycolysis, thus, its overexpression would provide cancer cells with adequate glycolytic flux and further the shift towards aerobic glycolysis." (PMID 23420667, 2013). "Hyperglycolysis, along with increased HK2 expression and activity, has been reported in a variety of cancers." (PMID 23071593, 2012). "The overexpression of HK2 in cancer is thought to provide cancer cells with a growth advantage due to increase glycolytic flux by promoting the first step of glycolysis and thus promoting/inducing the shift towards aerobic glycolysis." (PMID 22691140, 2012). "HK2 is overexpressed in many human cancers and has been reported to be involved in maintenance of the malignant state of tumors." (PMID 22691140, 2012). "A substantial amount of data supports hexokinase-2 (HK2) as a molecular target for the diagnosis and treatment cancer." (PMID 23071593, 2012). "Some experiments testified that HK-2 is binding to mitochondria in carcinoma tissue, such mode of binding is helpful for HK-2 making use of energy produced by mitochondria." (PMID 20846459, 2010). "HK2 (Hexokinase 2), involved in the increased rate of glycolysis seen in rapidly growing cancer cells, was increased 2.2-fold." (PMID 19284555, 2009). "HK2 might regulate the translation of several other key mRNAs involved in cancer-relevant signaling pathways." (PMID 40956859, 2025). "Additionally, genistein treatment led to a significant reduction in HK2 expression, an enzyme central to the Warburg effect and cancer cell survival in aggressive tumors." (PMID 39859445, 2025). "Targeting HK2 has shown significant promise in disrupting cancer metabolism." (PMID 40433363, 2025). "Arsenic induced ROS formation and activated the NF-κB signaling pathway via the phosphorylation of p65 at the Ser536 and Ser276 sites, resulting in the upregulation of hexokinase-2 (HK2), a key mediator of aerobic glycolysis and a promoter of cell proliferation in various cancer cell lines." (PMID 39567405, 2025). "Targeting HK2 is crucial, as it plays a significant role in maintaining glycolysis in cancer cells." (PMID 40739477, 2025). "Studies have found that HIF-1α could combine with HK2 promoter sites, raise the expression of HK2 to promote cancer cell to glucose metabolic reprogramming." (PMID 39991762, 2025). "Among the four HK isoforms in mammals, HK2 is a cancer-specific enzyme regulated by HIF1 and c-Myc." (PMID 40612109, 2025).